HSF1 (heat shock transcription factor 1)
Diseases named in the same sentence as HSF1 in open-access papers (continued):
Sharing a sentence is not in itself a finding about the gene and the disease.
gastric cancer (continued). "Interestingly, galectin-3 interacted with HSF-1 directly, which facilitated nuclear-localization and binding on neogenin-1 promoter to drive its transcription and gastric cancer cell motility." (PMID 24930499, 2014). "Therefore, we demonstrate herein the effects of neogenin-1 on gastric cancer cell proliferation and migration, as well as the regulation of its expression by HSF-1 and galectin-3 interactions." (PMID 24930499, 2014). "Furthermore, HSF1 promotes the proliferation, invasion, and migration of gastric cancer cells." (PMID 34064083, 2021). "Moreover, we suggest a role of HSF1 as a potential biomarker of gastric cancer." (PMID 34064083, 2021). "Additionally, TCGA data also revealed the overexpression of HSF1 in gastric cancer tissues." (PMID 34064083, 2021). "The interaction of HSF1 with MORC2 mediates the invasion and migration of gastric cancer cells through inhibiting ArgBP2, which is an important regulator of cytoskeleton and cellular motility." (PMID 34064083, 2021). "Gastric cancer cells treated with H. pylori CagA inhibited apoptosis through stimulating FUT4 fucosylation, which activated HSF1 transcription." (PMID 34064083, 2021). "In addition, several reports have demonstrated the pro-survival and pro-carcinogenetic role of YY1, SP1 and HSF1 in gastric cancer (GC) development." (PMID 32751694, 2020). "Therefore, HSF1 and PDK3 promote glycolysis and chemoresistance in gastric cancer through a positive feedback loop." (PMID 34064083, 2021). "Furthermore, we also determined the prognostic value of HSF1 expression in early (TNM stages I and II) and advanced (TNM stages III and IV) gastric cancer." (PMID 30326922, 2018). "Similarly, HSF1 stimulates the expression of pyruvate dehydrogenase kinase 3 (PDK3), which promotes glycolysis that supports cancer progression and chemoresistance in gastric cancer cells." (PMID 37153737, 2023). "Although not yet identified in gastric cancer, many HSF1 mediated inhibitors are being studied." (PMID 34064083, 2021). "Although HSF1 levels have not been compared at different cancer stages, they are shown to be elevated in gastric cancer patient tissues and are proposed to exhibit a potential role in diagnosing gastric cancer." (PMID 34064083, 2021). "Regarding HSF1, its activity is mainly induced in response to different stressful conditions such as heat shock, oxidative stress or proteotoxic stress: this may account for the lack of effect on UBC and UBB gene transcription in HSF1 silenced gastric cancer cells." (PMID 32751694, 2020). "The lack of effect on UBC and UBB gene transcription in HSF1-silenced gastric cancer cells may depend on the fact that HSF1 is a stress-activated TF, while for YY1 we evaluated different target genes in the siYY1-transfected cells and we found that they are differently affected by YY1 knockdown." (PMID 32751694, 2020).
colon carcinoma (18 papers, 2012 to 2024). "In other words, the increased expression of HSF1 may promote the occurrence of ulcerative colitis-associated colon cancer." (PMID 35645809, 2022). "Moreover, Hsf1 was recently implicated in mediating the transition from chronic inflammation to colon cancer by mediating ECM remodeling." (PMID 34169837, 2021). "It was found that the incubation of A549 or DLD1 colon cancer cells with either human monocytes or THP1 monocyte-like cells activated HSF1 and increased resistance to etoposide." (PMID 38280079, 2024). "In this work, activation of the transcriptional regulator, heat shock factor 1 (HSF1) in colon fibroblasts was reported to play a crucial role in ECM remodeling, whereas loss of stromal HSF1 prevented ECM remodeling and progression to colon cancer." (PMID 37397375, 2023). "Taken together these findings suggest not only that our model recapitulates early stages of colon cancer, but also highlight the potential role of stromal HSF1 in ECM remodeling in human CAC." (PMID 33288768, 2020). "HSF1 supports highly malignant human cancers, including the most aggressive forms of breast, lung, and colon cancer." (PMID 24800749, 2014). "Furthermore, it has recently been shown that HSF1 can indirectly influence the resistance of colon cancer cells to oxaliplatin through the activation of protective autophagy and control the expression of multidrug resistance genes." (PMID 38280079, 2024). "Loss of HSF1 abrogates ECM assembly by colon fibroblasts in cell culture, prevents ECM remodeling in a mouse model of inflammation-induced colon cancer, and significantly inhibits progression to colon cancer." (PMID 33559835, 2021). "Furthermore, QU reduces temperature-dependent expression of heat-shock protein-70 (HSP-70) by downregulating heat-shock-transcription factor 1 (HSF-1) in vitro, and in vivo, as shown in colon carcinoma and Ehrlich ascites tumor (EAT) in mice." (PMID 32709143, 2020). "Thus, HSF1-dependent ECM remodeling plays a crucial role in mediating inflammation-driven colon cancer." (PMID 33288768, 2020). "Moreover, overexpression of HSF1 has been reported in a multitude of cancers including liver, lung, breast and colon cancers where high HSF1 levels were related to unfavorable prognosis." (PMID 31540420, 2019). "Furthermore, the application of CL-43 also resulted in a reduction of active (phosphorylated) HSF1 form in colon cancer cells from human samples and the simultaneous increase of their sensitivity to cytotoxic effect of CQ even after the reaction with THP1 monocytes." (PMID 38280079, 2024). "Therefore, HSF1 is a promising target for colon cancer treatment and chemoprevention." (PMID 32110802, 2020). "Also, HSF1 was shown to colocalize with SFRS10 in human colon cancer cell lines." (PMID 24098751, 2013). "Together with an oncogenic driver, and in the context of chronic inflammation, HSF1 is activated, leading to massive ECM remodeling and, consequently, inflammation-driven colon cancer." (PMID 33288768, 2020). "Here we find that the transcriptional master regulator HSF1 is activated during early stages of inflammation in the colon, and its activation leads to remodeling of the ECM, supporting the development of colon cancer." (PMID 33288768, 2020). "We find that HSF1 is activated in stromal fibroblasts during early stages of inflammation, and its activation leads to ECM remodeling, supporting the development of colon cancer." (PMID 33288768, 2020). "To test whether HSF1-dependent ECM remodeling promotes cancer in vivo, we exposed WT and Hsf1 null mice to an inflammation-driven colon cancer model." (PMID 33288768, 2020). "Ruth Scherz-Shouval (Weizmann Institute of Science, Israel) showed that heat shock factor 1 (HSF1) is activated in response to inflammatory signals in stromal fibroblasts of the gut, and that its activation promotes ECM remodeling, leading to the development of colon cancer." (PMID 33559835, 2021).
Obesity (18 papers, 2012 to 2025). Accumulation of substantial excess body fat. "The present study aimed to identified novel natural HSF1 activator and evaluated the therapeutic effects of the newly discovered compound on obesity-associated metabolic disorders and the molecular mechanisms of these effects." (PMID 38333010, 2024). "This further substantiates that HSF1 is a critical target through which WMW exerts its therapeutic effects on obesity, indicating the importance of the HSF1 pathway in the browning process and overall metabolic regulation." (PMID 39754217, 2025). "These functions suggest that HSF1 has significant potential in regulating adipose tissue metabolism and addressing obesity." (PMID 39754217, 2025). "This is significant as suppressed expression of both HSP70 and HSF1 is commonly observed in adipose tissue, liver, skeletal muscle and vascular beds of individuals with obesity and type-2 diabetes mellitus." (PMID 39716481, 2025). "WMW represents a potent therapeutic strategy for obesity, promoting metabolic health and beneficial modulation of adipose tissue through an HSF1-dependent pathway." (PMID 39754217, 2025). "This comprehensive approach demonstrates that WMW induces an increase in HSF1 expression, integral to the browning process and the potential therapeutic modulation of adipose tissue in obesity." (PMID 39754217, 2025). "Pharmacological inhibition of HSP90AA1 in mice with diabetes or diet-induced obesity and IR improves insulin sensitivity through the activation of HSF1, a key regulator of stress response." (PMID 40004184, 2025). "This study verified a proof of principle that pharmacological activation of the HSF1/PGC-1α axis effectively counteracts obesity and induces a thermogenic program in adipose tissue." (PMID 38333010, 2024). "Our findings highlight the importance of activating the HSF1/PGC-1α axis for obesity treatment by increasing adipose thermogenesis." (PMID 38333010, 2024). "Previously, we established a novel HSF1/PGC-1α axis activator screening system and identified the clinical hepatoprotective agent matrine as a robust HSF1/PGC-1α axis activator that efficiently alleviated obesity by inducing a thermogenic program in mice." (PMID 38333010, 2024). "Our third aim was to investigate the efficacy and potential mechanism by which pharmacological stimulation of HSF1 alleviated obesity." (PMID 38333010, 2024). "pTSL@(P+I) effectively upregulates UCP1 and COX5B expression by activating the transcription axis of PPARγ/PGC1α and HSF1/PGC1α, thereby promoting white adipose tissue browning and reducing obesity." (PMID 39195401, 2024). "This nanocomplex effectively upregulates UCP1 and COX5B expression by activating the transcription axis of PPARγ/PGC1α and HSF1/PGC1α, thereby promoting white adipose tissue browning and improving obesity." (PMID 39195401, 2024). "We previously showed obesity suppresses BAT HSF1 and the HSF1-induced ADH5 expression." (PMID 40631281, 2025). "Notably, HSF1 levels are more abundant in thermogenic adipocytes and restoration of HSF1 in BAT protects against obesity-associated BAT dysfunction." (PMID 40631281, 2025). "Thus, activation of the HSF1/PGC-1α axis presents a promising strategy for developing potential anti-obesity agents." (PMID 38333010, 2024). "Based on the demonstration that the pharmacological stimulation of HSF1 could be used to treat obesity." (PMID 38333010, 2024). "While HSF4 has not yet been directly linked to obesity or metabolic dysfunction, HSF1, another Heat Shock Transcription Factor is known to promote adipocyte browning via mitochondrial regulation." (PMID 38781157, 2024). "Furthermore, sensing local mild thermal effects and activating thermogenesis through HSF1, beige fat can effectively resist and treat obesity, as well as ameliorate metabolic disorders such as IR and hepatic lipid deposition." (PMID 39872144, 2024).
Obesity (continued). "Second, we aimed to explore whether activation of HSF1 can induce a thermogenic program and be a practicable therapeutic strategy for obesity treatment." (PMID 38333010, 2024). "In humans, an orthologous HSF-1-mediated signaling system may be dysregulated in diabetes, cancer and obesity." (PMID 23116063, 2012). "HSF1 has been unveiled to be a master regulator in the heat shock response and in responses to environmental conditions such as metals and so forth 70 promotes hematopoietic stem cell fitness and proteostasis in response to ex vivo culture stress, activates beige fat metabolism against obesity." (PMID 37009226, 2023). "To further ascertain that HSF1 is a target for WMW in the treatment of obesity, and in conjunction with previous studies, we chose DTHIB as an inhibitor of HSF1." (PMID 39754217, 2025). "Activating the HSF1/PGC-1α axis in adipose tissues has been reported to induce thermogenesis in mice, which presents a promising therapeutic avenue for obesity treatment." (PMID 38333010, 2024). "However, it is metabolically devastating that, in obesity and type-2 diabetes mellitus, decreased expression of both HSP70 and HSF1 is a common feature detected in adipose tissue, liver, skeletal muscle and vascular beds of patients." (PMID 39716481, 2025). "Celastrol activates HSF1, as a result, increasing energy expenditure, enhancing mitochondrial function in fat and muscle, as well as protecting against obesity, insulin resistance, and hepatic steatosis in mice fed HFD; the effects were totally abolished in HSF1 knockout mice." (PMID 36009315, 2022). "Using Lamin B, Tubulin and HSF-1 as internal controls, HDAC4 was predominantly found in the cytoplasm in both groups suggesting that obesity does not trigger a change in the localization of HDAC4." (PMID 24086512, 2013).
cardiac hypertrophy (14 papers, 2017 to 2025). "Previous studies have reported that HSF1 deficiency accelerated the transition from pressure overload-induced cardiac hypertrophy to HF." (PMID 34504645, 2021). "Taken together, deficiency of HSF1 deteriorated myocardial hypertrophy provoked by hypoxia in vitro, indicating a protective role of HSF1 in the hypoxia‐induced myocardial hypertrophy." (PMID 29992755, 2018). "Third, the underlying mechanism by which HSF1 attenuated ischaemia‐induced cardiac hypertrophy is associated with the blockage of the JAK2/STAT3 pathway." (PMID 29992755, 2018). "Deficiency of HSF1 by siRNA transfection notably increased the hypoxia‐induced myocardial hypertrophy in NRCMs." (PMID 29992755, 2018). "As the deficient HSF1 resulted in a deteriorated cardiac hypertrophy and heart failure, we next explored whether an enhanced phosphorylation of HSF1 abrogates the maladaptive cardiac hypertrophy induced by MI in HSF1 TG mice." (PMID 29992755, 2018). "Loss of HSF1 augmented hypertrophic response of CMs to ischaemia, indicating that the reduction of HSF1 activity may promote the progression of cardiac hypertrophy and the transition to heart failure in vivo." (PMID 29992755, 2018). "In this study, using LAD ligation in HSF1 KO and TG mice, together with hypoxic treatment in NRCMs infected with adenovirus of HSF1 SiRNA, we uncovered that deficiency of HSF1 deteriorated cardiac hypertrophy and cardiac dysfunction after MI through enhancing the activity of JAK2/STAT3 signalling." (PMID 29992755, 2018). "Evidence supports CaMKII-dependent phosphorylation of class IIa HDACs (Ser467/Ser632 in HDAC4), linking CaMKII to MEF2 activation in cardiac hypertrophy, and interactions with NF-κB and HSF1 further expand its nuclear repertoire." (PMID 41283247, 2025). "The several main regulators of PPARα such as HSF-1, ATGL, RXRα, and ERRα were detected, the downregulation of which are associated with cardiac hypertrophy." (PMID 35479323, 2022). "Next, we used mechanical stretch to establish a pressure-stimulated myocardial hypertrophy model and discovered an increased expression of both HSF1 and ALDH2." (PMID 32626739, 2020). "We also observed that, in the early stage of compensated heart hypertrophy, HSF1 and the protein recorded an increased expression." (PMID 32626739, 2020). "Further in the research on cardiomyocytes in vitro, we found that, as the expression of myocardial hypertrophy gene increased, HSF1 and ALDH2 also correspondingly increased." (PMID 32626739, 2020). "The present study brought a novel tragedy that controlling cardiac hypertrophy induced by cardiac ischaemia through regulation of HSF1." (PMID 29992755, 2018). "Inversely, HSF1 TG mice showed significantly ameliorated cardiac hypertrophy and heart failure 1 week after LAD ligation compared to their WT littermates." (PMID 29992755, 2018). "Together, these in vivo data from HSF1 TG mice further demonstrated that HSF1 is able to inhibit the pathological cardiac hypertrophy and promote the cardiac dysfunction induced by MI." (PMID 29992755, 2018). "Our findings indicated that HSF1 is critically involved in the myocardial hypertrophy evoked by MI, implying a promising therapeutic potential of HSF1 in MI patients." (PMID 29992755, 2018). "The HSF1 TG mice showed significant attenuation of pathological cardiac hypertrophy evidenced by preserved HR, decreased LVAWd, LVIDd and increased EF 1 week after MI compared to WT mice." (PMID 29992755, 2018). "On the basis of these observations, we concluded that the phosphorylation of HSF1 is a potential mechanism of the cardiac hypertrophy occurred in the early stage of MI." (PMID 29992755, 2018). "Collectively, these in vivo data, consistent with the observations in vivo, further supported that HSF1 is necessary for the development of cardiac hypertrophy and the transition to heart failure in the early stage of MI." (PMID 29992755, 2018).